MDFI (MyoD family inhibitor)
Description:
Inhibits the transactivation activity of the Myod family of myogenic factors and represses myogenesis (By similarity). Acts by associating with Myod family members and retaining them in the cytoplasm by masking their nuclear localization signals (By similarity). Can also interfere with the DNA-binding activity of Myod family members (By similarity). Plays an important role in trophoblast and chondrogenic differentiation (By similarity). Regulates the transcriptional activity of TCF7L1/TCF3 by interacting directly with TCF7L1/TCF3 and preventing it from binding DNA (By similarity). Binds to the axin complex, resulting in an increase in the level of free beta-catenin (By similarity). Affects axin regulation of the WNT and JNK signaling pathways (By similarity). Regulates the activity of mechanosensitive Piezo channel.
Synonyms: I-mfa; I-MF
Tractability: PROTAC: ubiquitination databases record sites on it.
Gene: Protein-coding gene on chromosome 6 (41,636,840 to 41,654,246, forward strand). Ensembl gene ENSG00000112559.
Subcellular location: Nucleus; Cytoplasm
Subcellular location (Human Protein Atlas): Nucleoplasm
Gene Ontology:
Molecular function: identical protein binding; protein binding; protein sequestering activity; transcription regulator inhibitor activity
Biological process: maintenance of protein location in cell; dorsal/ventral axis specification; negative regulation of DNA-templated transcription; negative regulation of transcription by RNA polymerase II; negative regulation of Wnt signaling pathway; regulation of JNK cascade; regulation of Wnt signaling pathway; regulation of gene expression
Cellular component: cytoplasm; nucleus
Genetic constraint (gnomAD): Loss-of-function variants: 16 observed, 17.93 expected, observed/expected ratio (o/e) 0.89, 90% interval 0.6 to 1.36. The upper end of that interval is the gene's LOEUF score, 1.36, which puts it in group 5 of 6, group 1 being the genes least tolerant of losing a copy. Missense variants: 314 observed, 296.36 expected, observed/expected ratio (o/e) 1.06, 90% interval 0.96 to 1.16. Synonymous variants: 145 observed, 131.55 expected, observed/expected ratio (o/e) 1.1, 90% interval 0.96 to 1.26.
Homologues: Orthologues: chimpanzee MDFI (99% identical), macaque MDFI (96% identical), dog MDFI (91% identical), pig MDFI (91% identical), rabbit MDFI (91% identical), guinea pig MDFI (83% identical), rat Mdfi (83% identical), mouse Mdfi (79% identical), zebrafish mdfi (48% identical), tropical clawed frog mdfi (36% identical). Paralogues in human: MDFIC (40% identical), MDFIC2 (15% identical).
Diseases named in the same sentence as MDFI in open-access papers:
MDFI is named in the same sentence as 22 diseases in open-access papers, as found by Europe PMC text mining. Sharing a sentence is not in itself a finding about the gene and the disease. The quoted sentences say what the papers report.
colorectal cancer (2 papers, 2020 to 2024). A primary or metastatic malignant neoplasm that affects the colon or rectum. "In conclusion, MDFI promotes the proliferation and tolerance to chemotherapy of colorectal cancer cells, partially through the activation of the AKT signaling pathway by the binding to ITGB4/LAMB3." (PMID 38375821, 2024). "Our study sheds light on the significance of the MDFI as a compelling therapeutic target in colorectal cancer (CRC)." (PMID 38375821, 2024). "Previous studies have shown that MDFI is hypermethylated in colorectal cancer, which would suggest reduced MDFI transcription." (PMID 32457453, 2020). "Similar to colorectal cancer, MDFI was up- and MDFIC downregulated in breast, ovarian and prostate cancer, but both were overexpressed in brain, gastric and pancreatic tumors that implies MDFIC to also promote tumorigenesis in certain tissues." (PMID 32457453, 2020). "Mirroring these different expression patterns, MDFI stimulated and MDFIC inhibited growth of HCT116 colorectal cancer cells." (PMID 32457453, 2020). "To assess if MDFI or MDFIC can affect cancer cells, we overexpressed these proteins in human HCT116 colorectal cancer cells and then examined their growth." (PMID 32457453, 2020). "Further, MDFI and MDFIC interacted with Jumonji C domain-containing (JMJD) 1 A, a histone demethylase and epigenetic regulator involved in colorectal cancer." (PMID 32457453, 2020). "In this study, we provide the first evidence that MDFI and MDFIC are involved in colorectal cancer." (PMID 32457453, 2020). "Hence, we examined the role of MDFI and MDFIC in colorectal cancer cells." (PMID 32457453, 2020). "Finally, we wondered if MDFI and MDFIC may not only be involved in colorectal cancer, but also in neoplasms of other tissues." (PMID 32457453, 2020).
colorectal tumor (2 papers, 2020 to 2024). "This is based on the following evidence: First, we showed that MDFI is overexpressed, while MDFIC is downregulated in colorectal tumors, and high MDFI but low MDFIC levels are associated with more aggressive disease." (PMID 32457453, 2020). "The TCGA database showed that MDFI gene expression levels were upregulated in colorectal tumor tissues compared with those in normal tissues." (PMID 38375821, 2024). "Using published microarray data, we observed that, identical to colorectal tumors, MDFI and MDFIC exhibited up- and downregulation, respectively, in prostate, breast and ovarian cancer." (PMID 32457453, 2020). "Lastly, it is noteworthy that JMJD1A has been implicated in breast, gastric, ovarian and prostate cancer, suggesting that the interaction of JMJD1A with MDFI/MDFIC is relevant beyond colorectal tumors." (PMID 32457453, 2020). "This is in contrast to our bioinformatics results, showing upregulation of MDFI in colorectal tumors." (PMID 32457453, 2020). "Together, these data suggest that MDFI up- and MDFIC downregulation are connected to colorectal tumor formation and possibly also the aggressiveness of the disease." (PMID 32457453, 2020). "We discovered that MDFI is up- and MDFIC downregulated in colorectal tumors." (PMID 32457453, 2020). "In addition, we discovered changes in the expression pattern of MDFI and MDFIC in colorectal tumors." (PMID 32457453, 2020).
gastric cancer (2 papers, 2024). A primary or metastatic malignant neoplasm involving the stomach. "In Chen Mi’s study, MDFI was shown to regulate glycolysis, which affects the proliferation of gastric cancer cells via the Wnt/β-catenin pathway." (PMID 38375821, 2024). "Controversially, in tumour cells, the inhibition of MDFI attenuates the proliferation and glycolysis of Helicobacter pylori‐infected gastric cancer cells by inhibiting Wnt/β‐catenin pathway." (PMID 39046458, 2024).
acute kidney injury (1 paper, 2022). Sudden and sustained deterioration of the kidney function characterized by decreased glomerular filtration rate, increased serum creatinine or oliguria. "The expression of ESM1 and RALYL were markedly increased in control samples, while EHBP1L1, FBXW4, MDFI, and MDM4 were markedly increased in acute kidney injury samples." (PMID 36313991, 2022). "Six hub genes (MDFI, EHBP1L1, FBXW4, MDM4, RALYL, and ESM1) were identified as potentially predictive of an acute kidney injury." (PMID 36313991, 2022).
cardiac hypertrophy (1 paper, 2024). "To conclude, our research offers substantial proof of miR‐128 and MDFI's combined molecular interaction, playing a significant role in the onset of cardiac hypertrophy and HF." (PMID 39046458, 2024). "Subsequently, we delved into the pathological consequences of miR‐128 and MDFI interaction on cardiac hypertrophy and HF." (PMID 39046458, 2024). "In the current work, utilizing isolated cardiomyocytes cell lines and animal models of isoproterenol (ISO) infusion, our research elucidated the detrimental role of the miR‐128/MDFI interplay in advancing cardiac hypertrophy and HF, through the upregulation of the Wnt1/β‐catenin signalling axis." (PMID 39046458, 2024).
endometriosis (1 paper, 2026). The growth of functional endometrial tissue in anatomic sites outside the uterine body. "Similarly, in JAR cells co-cultured with gestational epithelial endometriosis, NR2F2 and IGF2 were upregulated, whereas MDFI, SP3, and RDH10 were downregulated." (PMID 42282918, 2026).
gastric tumors (1 paper, 2020). "However, both MDFI and MDFIC were upregulated in brain, pancreatic and gastric tumors." (PMID 32457453, 2020).
myeloid neoplasm (1 paper, 2022). Proliferation of myeloid cells originating from a primitive stem cell. "A previous study has demonstrated that the loss of MDFI was related to human BC and myeloid neoplasm via negative regulation of the Wnt pathway." (PMID 36046013, 2022).
rectal mucinous adenocarcinomas (1 paper, 2020). "The Cancer Genome Atlas (TCGA) data set21 revealed that MDFI mRNA was significantly upregulated in cecum, colon, colon mucinous, rectal and rectal mucinous adenocarcinomas compared to normal colon and rectum, while MDFIC was on average downregulated." (PMID 32457453, 2020).
cancer (5 papers, 2011 to 2024). A tumor composed of atypical neoplastic, often pleomorphic cells that invade other tissues. "Altogether, our data suggest a tumor modulating function for MDFI and MDFIC in colorectal and other cancers that may involve their interaction with JMJD1A and a MDFIC→HIC1 axis." (PMID 32457453, 2020).
tumor (5 papers, 2011 to 2024). "In addition, MDFI is over expressed in CRC tumors and high expression of MDFI is associated with tumor metastasis." (PMID 35114976, 2022). "The results revealed that the PI3K-AKT pathway was active in tumor cells and that MDFI upregulated the PI3K-AKT pathway by directly regulating LAMB3 and ITGB4." (PMID 38375821, 2024). "Perplexingly, despite their high homology, they appear to act in opposite ways, namely MDFI as a tumor promoter and MDFIC as a repressor." (PMID 32457453, 2020). "Similar MDFI up- and MDFIC downregulation was observed in other microarray data sets, and MDFI appears to be also more expressed in metastatic compared to primary tumor sites." (PMID 32457453, 2020). "This implicates that MDFI may generally perform tumor promoting activities, whereas MDFIC might tissue-specifically inhibit or stimulate tumorigenesis." (PMID 32457453, 2020). "Presently, it is essentially unknown whether MDFI and MDFIC play any role in tumor formation." (PMID 32457453, 2020). "As such, the results of the shown RNA interference experiments do not allow us to strengthen or refute the hypothesis that MDFI exerts tumor-promoting and MDFIC tumor-suppressing activities." (PMID 32457453, 2020).
infection (1 paper, 2025). The state of being infected such as from the introduction of a foreign agent such as serum, vaccine, antigenic substance or organism. "Knocking down MyoD family inhibitor (MDFI) suppresses H. pylori-induced GC cell proliferation and enhanced glycolysis; the infection promotes MDFI expression and activates the Wnt/β-catenin pathway." (PMID 41158522, 2025).
MDFI also shares sentences with these, for which no sentence is quoted: breast carcinoma (2 papers); ovarian carcinoma (2); prostate carcinoma (2); colon cancer (1); glomerulosclerosis (1); heart failure (1); hepatocellular carcinoma (1); kidney disease (1); pancreatic cancer (1); renal fibrosis (1).